CLDN1 (claudin 1)
Diseases named in the same sentence as CLDN1 in open-access papers (continued):
Sharing a sentence is not in itself a finding about the gene and the disease.
Erythema (2 papers, 2023 to 2025). Redness of the skin, caused by hyperemia of the capillaries in the lower layers of the skin. "By suppressing this inflammatory cascade, ERG was able to alleviate erythema and restore the integrity of the skin’s physical barrier, evidenced by the restored expression of key tight junction proteins Claudin-1, Occludin, and ZO-1." (PMID 41295413, 2025).
fatty liver (2 papers, 2025). "In the HFD-induced fatty liver mouse model, the protein level of Claudin-1 was significantly reduced, suggesting that the HFD may have disrupted intestinal barrier function." (PMID 40948779, 2025).
glomerular disease (2 papers, 2014 to 2023). "In the present study, we investigated the expression of claudin-1 and its colocalization with ZO-1 in various human glomerular diseases including IgA nephropathy, purpura nephritis, ANCA associated vasculitis (MPO-ANCA and PR-3 ANCA), anti-GBM-RPGN, and lupus nephritis." (PMID 24868462, 2014).
glomerulosclerosis (2 papers, 2022 to 2023). A hardening of the kidney glomerulus caused by scarring of the blood vessels. "NMN treatment mitigated glomerulosclerosis and ameliorated the reduced Sirt1 expression and elevated Claudin-1 expression in the kidneys of the mice." (PMID 35962139, 2022).
hyperuricemia (2 papers, 2022 to 2024). An abnormally high level of uric acid. "A recent study pointed out that intestinal barrier dysfunction was reflected by the downregulation of the expression of ZO-1, occludin and claudin-1, leading to hyperuricemia in mice." (PMID 35736894, 2022).
injury (2 papers, 2018). Damage inflicted on the body as the direct or indirect result of an external force, with or without disruption of structural continuity. "However, a similar phenomenon was observed in a model of traumatic brain injury in which the associated increase in dextran flux in the absence of a change in TEER was associated with a decrease in Claudin-1 mucosal expression." (PMID 30154689, 2018). "The expressions of the majority of claudin isoforms (CLDN1, 2, 5, 10, 11, 14, 19, 20, and 22) were decreased after nerve injury while the expressions of a few isoforms (CLDN4, 15, and 23) were increased." (PMID 30425652, 2018).
intestinal tumors (2 papers, 2014 to 2023). "Analysis of intestinal tumors from VilCre Lin28bhi mice showed that the tumors with higher LIN28B expression had higher CLDN1 expression when compared with tumors from VilCre Lin28blo mice." (PMID 37318881, 2023).
invasive ductal carcinoma (2 papers, 2019 to 2020). "On the other hand, three GCDFP-15 negative cases showed strong Claudin 1 positivity: one was a lympho-epithelioma-like carcinoma, the second was an invasive ductal carcinoma with abundant tumour infiltrating lymphocytes and the third had features of micropapillary carcinoma." (PMID 31044387, 2020).
ischemic stroke (2 papers, 2023 to 2025). A stroke disorder caused by obstruction of blood flow to the brain, due to thrombotic (local blood clot formation) or embolic (due to a blood clot or other material traveling from another site) event. "Ischemic stroke triggered an initial elevation of claudin-1 protein at 1 day post-tMCAO, followed with a significant loss of claudin-1 protein expression by 5 days post-tMCAO (p < 0.05)." (PMID 38107410, 2023). "TZP ameliorates BBB dysfunction and protects against ischemic stroke by activating C/EBP-α signaling and restoring Claudin-1-mediated tight junction integrity." (PMID 40702450, 2025). "Using a middle cerebral artery occlusion (MCAO) mouse model of ischemic stroke, we assessed the effects of TZP on neurological deficits, BBB permeability, and the expression of tight junction (TJ) proteins, particularly Claudin-1." (PMID 40702450, 2025).
leukaemia (2 papers, 2006 to 2015). "Although the CLDN1 band is present in addition to HOXB6, the role of CLDN1 in leukemia initiation is not clear and needs further investigation." (PMID 26606454, 2015).
leukoaraiosis (2 papers, 2019 to 2021). "Our data has demonstrated that the abnormal expression of claudin-1 and claudin-3 regulates the pathological progression of leukoaraiosis by governing the viability and myelination of oligodendrocytes." (PMID 34008771, 2021). "Our results revealed that in addition to SOX10, the expression levels of claudin-1, claudin-3, and myelinogenesis-related proteins were prominently downregulated in leukoaraiosis patients, compared to those in healthy controls." (PMID 34008771, 2021). "However, the roles of claudin-1 and claudin-3 in oligodendrocytes and leukoaraiosis are still not well-defined." (PMID 34008771, 2021).
mastitis (2 papers, 2024 to 2026). Inflammation of breast tissue during lactation or postpartum due to an obstructed duct or infection. "Expression of intestinal tight junction proteins (e.g., Claudin-1, Occludin) is significantly downregulated (by ~40%), causing endotoxin translocation (serum LPS increases ~3-fold) and disruption of the blood-milk barrier, increasing mastitis risk by 2-3 times." (PMID 41766889, 2026). "Tissue immunofluorescence analysis showed that when compared with the healthy mammary gland, the mammary glands with subclinical mastitis exhibited notably lowered ZO-1, occludin and claudin-1 expressions, as well as clearly elevated LC3 plus beclin-1 expressions at the protein level." (PMID 39765775, 2024). "It has been found, through research, that the occurrence of mastitis will destroy the integrity of tight junctions (TJs), including a decrease in the expression of TJ proteins (claudin-1, occludin, ZO-1, etc.), thereby increasing their permeability and damaging the health of the mammary gland." (PMID 39765775, 2024). "Moreover, Western blotting assay also manifested remarkably decreased ZO-1, claudin-1 and occludin expressions in subclinical mastitis by contrast with those in the healthy ones, while the opposite trends in beclin-1 and LC3 expressions were obtained." (PMID 39765775, 2024).
medullary carcinomas (2 papers, 2014 to 2024). "Only one patient was positive for CLDN1, CLDN2, and CLDN7 expression, and two of three patients with medullary carcinomas were positive for CLDN4 expression." (PMID 25393310, 2014). "No goiter, medullary thyroid cancer, or anaplastic thyroid cancer expressed claudin-1." (PMID 39458944, 2024).
mucositis (2 papers, 2019 to 2025). Mucositis is inflammation and damage of the mucous membranes lining the mouth and other parts of the gastrointestinal (GI) tract. "Induced mucositis is accordingly linked to a reduction in the expression of the Claudin-1 gene." (PMID 31921383, 2019). "5-FU-induced mucositis disrupts the intestinal epithelial barrier by altering the expression of tight junction proteins such as ZO-1, occludin, and claudin-1, essential for cell adhesion and permeability regulation." (PMID 40244381, 2025).
multiple sclerosis (2 papers, 2019 to 2026). A progressive autoimmune disorder affecting the central nervous system resulting in demyelination. "In fact, endothelial specific inducible ectopic expression of claudin-1 in BBB endothelium reduces BBB leakiness in an animal model of multiple sclerosis and ameliorates clinical signs of the disease further supporting absence of claudin-1 at the BBB." (PMID 31671721, 2019).
oral cancer (2 papers, 2021 to 2024). "Conversely, increased CLDN1 expression has been associated with enhanced invasive and metastatic behaviours in colon, hepatocellular, and oral cancers." (PMID 39457456, 2024). "Silencing of CLDN1 results in decreased invasive potential and proliferation of oral cancer cells." (PMID 34822542, 2021).
periodontitis (2 papers, 2021 to 2025). An acute or chronic inflammatory process that affects the tissues that surround and support the teeth. "The periodontitis-affected gingival epithelium highly expressed tight junction genes claudin-1 (CLDN1) and E-cadherin (CDH1) (p < 0.001), while the average expression of occludin (OCLN) was also elevated, although this was not statistically significant." (PMID 41358003, 2025). "In the small intestine, experimental periodontitis significantly downregulated ZO-1 expression (P <0.05), and Claudin-1 and Occludin also showed less expression in experimental periodontitis mice." (PMID 35118014, 2021).
polycystic kidney (2 papers, 2015 to 2022). "Gene-based analysis also highlighted several other genes, including a gene implicated in polycystic kidney disease (TMEM207), a gene expressed at the tight junction of renal tubule epithelial cells (CLDN1), and a gene associated with cell proliferation (GNL2)." (PMID 36275661, 2022).
rheumatoid arthritis (2 papers, 2024 to 2026). A chronic, systemic autoimmune disorder characterized by inflammation in the synovial membranes and articular surfaces. "Our results point out that rheumatoid arthritis (RA) patients show differences in intestinal permeability compared to healthy controls due to decreasing claudin-1 levels." (PMID 39201334, 2024).
rosacea (2 papers, 2025). A chronic erythematous skin disorder that affects the face. "Moreover, we observed that GE1111 effectively preserved the expression of claudin 1, a critical tight junction protein essential for maintaining epidermal barrier integrity, which is often compromised in rosacea, leading to aggravated symptoms and potential secondary infections." (PMID 41296102, 2025). "Compared with healthy controls, KRT6A and KRT16 mRNA levels were significantly upregulated in rosacea, whereas CLDN1, CLDN16, OCLN, and KRT17 showed no significant changes, and CLDN23 was significantly downregulated." (PMID 40346694, 2025). "Analysis focused on claudin-1 due to its central role in LL-37-mediated barrier disruption; filaggrin and loricrin were not assessed but are often similarly affected in rosacea models." (PMID 41296102, 2025).
schwannoma (2 papers, 2022 to 2024). A benign, usually encapsulated slow growing tumor composed of Schwann cells. "The classic schwannoma was the only one that was completely negative for claudin-1 and showed strong reactivity for Sox10 and moderate reactivity for GFAP." (PMID 35622732, 2022). "Based on our results, we consider Sox10, claudin-1, GFAP, and Ki-67 useful in the diagnosis of NST, whereas CNPase was negative in almost all cases, except for classical schwannoma, which was only mildly positive." (PMID 35622732, 2022).
serous adenocarcinoma (2 papers, 2009 to 2014). An adenocarcinoma that is characterized by the presence of papillary patterns and cellular budding. "This is in agreement with a previous study that distinguished between endometrioid and serous carcinoma using immunohistochemistry and claudin 1–7 expression." (PMID 19440550, 2009). "In comparison, serous carcinoma samples expressed high levels of CLDN1 whereas mucinous and normal were low and clear cell levels were the lowest." (PMID 19440550, 2009).
skin cancer (2 papers, 2013 to 2018). "The data indicate that alterations found for Cldn-1, Cldn-4, ZO-1, and JAM-A are common for UV-induced skin tumors while the frequent loss of Ocln appears as specific for SCC." (PMID 23390516, 2013). "Looking for explanations for the common alterations of Cldn-1, Cldn-4 and ZO-1 identified in the various skin tumors, we hypothesized that chronic UV exposure might induce some of these changes." (PMID 23390516, 2013). "Because the alterations for Cldn-1, Cldn-4, and ZO-1 were observed in all UV- promoted skin tumors and a broader localization of Ocln was frequent in all tumor entities except for SCC, we wondered whether these alterations could also be identified in chronically sun-exposed skin." (PMID 23390516, 2013). "From this data we conclude that most TJ protein alterations observed in skin tumors are likely to be induced by UV-irradiation, but loss of Ocln and downregulation of Cldn-1 in the uppermost layers may not be related to UV." (PMID 23390516, 2013).
small cell lung carcinoma (2 papers, 2023 to 2025). Small cell lung cancer (SCLC) is a highly aggressive malignant neoplasm, accounting for 10-15% of lung cancer cases, characterized byrapid growth, and early metastasis. "In small cell lung cancer, overexpressed Cldn1 causes epithelial–mesenchymal transition, resulting in enhanced migration and reduced resistance to doxorubicin treatment." (PMID 40361399, 2025).
steatosis (2 papers, 2022 to 2024). Increased lipid within the cytoplasm of cells. "Moreover, LGG alleviated liver injury, steatosis, and intestinal barrier injury caused by alcohol, and enhanced ZO-1 and Claudin-1 expressions." (PMID 35603884, 2022). "Enhance the expression of ZO-1, Claudin-1 and Occludin, decrease the expression of LPS, TNF-α, IL-6 and IL-1β, enhance intestinal barrier, and reduce inflammatory response, hepatocyte steatosis and collagen fiber deposition." (PMID 39234554, 2024).
thyroid (2 papers, 2021 to 2024). "Claudin-1 staining patterns differed depending on the type of thyroid pathology and changed between cancers of different origins." (PMID 39458944, 2024). "The immunohistochemical expression of CD56 and claudin-1 was evaluated in 86 samples of thyroid lesions together with 10 samples of normal thyroid tissue." (PMID 34711014, 2021). "Considering the role of claudin-1 in thyroid premalignancy-to-malignancy transition, it has also been demonstrated that expression of claudin-1 increases in solitary dominant nodules (SDN) compared to normal gland tissue." (PMID 39458944, 2024).
type 1 diabetes (2 papers, 2024 to 2026). "They found that APS-1 significantly reduced insulin levels in type 1 diabetic (T1D) mice and improved the intestinal barrier function by regulating the expression of ZO-1, Occludin, and Claudin-1." (PMID 39215362, 2024).
type 2 diabetes (2 papers, 2023 to 2025). "Peanut skin procyanidins, including B1 and B2 forms, offered to type 2 diabetic mice preserved villus length and crypt depth, improved the gut barrier integrity by enhancing colon tight junction protein expression including zonula occludens-1, claudin-1 and occludin." (PMID 39980683, 2025).
acne (1 paper, 2023). An inflammatory process of the sebaceous glands which is characterized by comedones, nodules, papules and/or pustules on the skin. "It would be interesting to systematically investigate the expression levels and changes in barrier molecules and TJ components, especially CLDN-1 levels, to determine if and how they play a role in acne initiation and progression." (PMID 37958945, 2023).
acute pancreatitis (1 paper, 2024). An acute inflammatory process that leads to necrosis of the pancreatic parenchyma. "Similarly, reported that butyrate significantly increased the expression of Occludin, Claudin-1, and ZO-1 in a rat model of severe acute pancreatitis with intra-abdominal hypertension." (PMID 38731359, 2024).
allergic rhinitis (1 paper, 2022). Inflammation of the nasal mucous membranes caused by an IgE-mediated response to external allergens. "Furthermore, mRNA and protein expression levels of claudin-1 and occludin were increased by EOM treatment in allergic rhinitis, indicating that EOM is effective in defending the nasal barrier." (PMID 36578435, 2022).
ameloblastoma (1 paper, 2022). The most common odontogenic tumor, arising from the epithelial component of the embryonic tooth and usually affecting the molar-ramus region of the mandible or maxilla. "Previous study from our group demonstrated that claudin-1 is highly expressed in odontogenic epithelium of ameloblastic fibroma but was weak in ameloblast-like cell and stellate reticulum-like cells in ameloblastoma." (PMID 34808689, 2022).
apocrine carcinoma (1 paper, 2020). "It is concluded that all benign and malignant apocrine lesions of the breast have a consistent pattern of claudin 1, 3 and 4 expression, suggesting the presence of a specific pathway for the development of invasive apocrine carcinoma." (PMID 31044387, 2020).
atherosclerosis (1 paper, 2022). A disease characterized by the build-up of fatty material and calcium deposition in the arterial wall resulting in partial or complete occlusion of the arterial lumen. "In addition, the expression of tight junction proteins (claudin-1, occludin, and ZO-1) was significantly downregulated in atherosclerosis mice, indicating that the tight junctions structure was disrupted and that the tight junctions structure was disrupted." (PMID 36034838, 2022).
atopic march (1 paper, 2022). sequential manifestations of different allergic diseases such as eczema, asthma and rhinitis. "Airway- and GI tract-specific knockdown of CLDN1 in a mouse model of atopic march can also be a great approach to prove our hypothesis." (PMID 35844593, 2022).
Autoimmunity (1 paper, 2026). The occurrence of an immune reaction against the organism's own cells or tissues. "Collectively, Claudin 1 dysregulation likely leads to autoimmunity both indirectly through the loss of the epithelial barrier integrity and directly through the failure of the DC1 lineage to mature and to purge self-reactive T cells." (PMID 41481333, 2026). "Collectively, these results indicate that the DC1-intrinsic expression of Claudin 1 is essential for the prevention of multiorgan autoimmunity." (PMID 41481333, 2026). "Since Claudin 1 is required for the induction of central tolerance, we investigated whether its absence in DC1s would lead to autoimmunity." (PMID 41481333, 2026). "To determine whether the observed autoimmune phenotypes could occur independently of BM transplantation and competition between Claudin 1–sufficient and Claudin 1–deficient DC1, we analyzed nonchimeric XCR1iCreCldn1fl/fl mice for signs of autoimmunity." (PMID 41481333, 2026). "Also, Paneth cells (PCs) as the only cells of the immune periphery with an active Defa6 promoter (the driver of OVA in OVA+Cldn1+/+ and OVA+Cldn1−/− chimeras) showed similar numbers in the ileum of all BM chimeras, further supporting the negligible role of OTIIs in the observed autoimmunity." (PMID 41481333, 2026).
autosomal dominant polycystic kidney disease (1 paper, 2020). Autosomal dominant form of polycystic kidney disease. "Previous studies on MDCK II (Madin–Darby canine kidney), rat Sertoli (the key structure of blood-testis barrier) and ADPKD (autosomal dominant polycystic kidney disease) cell cultures demonstrated that nanomolar ouabain induces the expression of claudin-1, -2, -4 and -11." (PMID 32709081, 2020).
bowel obstruction (1 paper, 2021). "In the present study, the levels of claudin-1 gene expression and sIgA decreased as prolonged obstruction presenting a serious impairment of the intestinal mucosal barrier due to bowel obstruction." (PMID 34347831, 2021).
brain tumors (1 paper, 2021). "Metastatic brain tumors are known to have a disrupted inter-endothelial tight junction due to the downregulation of tight junction components, including claudin-1, claudin-5, and occludin." (PMID 34722268, 2021).
breast SCC (1 paper, 2020). "In esophageal and breast SCC, claudin-1 down expression was associated with tumor recurrence and reduction of relapse-free survival." (PMID 32518268, 2020).
cervical intraepithelial neoplasia (1 paper, 2016). "To clarify the role of CLDN1 in the development of cervical lesions, we tested the expression of CLDN1 in a cervical intraepithelial neoplasia (CIN) tissue microarray." (PMID 27974683, 2016).
cervical squamous cell carcinoma (1 paper, 2016). A squamous cell carcinoma arising from the cervical epithelium. "Amplicons of TERC and CLDN1 were also tested by FISH using a BAC probe in the cervical squamous cell carcinoma tissue microarray." (PMID 27974683, 2016).
childhood cancers (1 paper, 2025). "Our CAR-T therapy targeting five common membrane protein cancer antigens—EphB4, CLDN1, LAT1, ROBO1, and GPC3—may be effective against many solid tumors, including childhood cancers." (PMID 40076777, 2025).